MTOR (mechanistic target of rapamycin kinase)
Diseases named in the same sentence as MTOR in open-access papers (continued):
Sharing a sentence is not in itself a finding about the gene and the disease.
tumor (continued). "Moreover, it induced reactive oxygen species generation, Mitogen-activated protein kinase (MAPK) activation, and inhibition of PI3K/AKT/mTOR/S6K1 signaling pathway in these cells, a pathway which is essential in cell survival, proliferation, and angiogenesis of the tumor." (PMID 29351194, 2018). "As PGAM1 is critical for tumor growth and is abundant in cells with hyperactive mTOR unveiled in this study, we checked whether the enhanced PGAM1 expression was essential for RTK-PI3K-AKT-mTOR-mediated aerobic glycolysis and oncogenesis." (PMID 29362480, 2018). "We evaluated mTOR signaling by immunohistochemical analysis of phosphorylated S6 kinase (pS6K; reflecting target of rapamycin complex 1 [TORC1] signaling) and phosphorylated AKT (pAKT; reflecting TORC2 signaling) using archived tumor biopsy samples at the time of diagnosis (baseline)." (PMID 30410720, 2018). "Nevertheless, it must be emphasized that treatment with mTOR inhibitors alone may not exert long-lasting anti-tumor effects." (PMID 30200497, 2018). "Further dissection of how MAPK signaling and mTOR signaling cooperate and identification of unique adaptor molecules controlling SALL1 biological functions in tumor cells will be critical preludes for the application of SALL1 and tumor senescence as new targets for tumor therapeutic interventions." (PMID 29625565, 2018). "Presumably, uncontrolled or non-specific activation of mTOR and protein synthesis may result in severe negative consequences, such as tumor formation or cognitive impairment." (PMID 30158848, 2018). "Furthermore, the expression of PI3K/Akt/mTOR pathway-related proteins was also altered in xenograft tumor tissue isolated from QLXZD-treated mice, with the phosphorylation of Akt (T308), mTOR (Ser2448), and p70S6K (T389) being inhibited in the QLXZD-treated group." (PMID 29670523, 2018). "Singla and Bhattacharyya (2017) have brought evidence active that mTOR signaling is no longer required once tumor cells have undergone EMT and that its inhibition may promote autophagy induction in EMT cells." (PMID 30013478, 2018). "Despite the fact that none of the drugs were tested on any ccRCC cell lines, connectivity mapping of the tumour sample signatures (but not the group or subtype signatures) does reveal significant negative enrichment for 2 out of the 3 mTOR-inhibitors used against ccRCC (sirolimus and temsirolimus)." (PMID 29588458, 2018). "Moreover, PD-L1 antibody treatment induces membranous PD-L1 internalization, implying that it is membranous PD-L1 rather than cytoplasmic PD-L1 that is involved in Akt/mTOR signaling in tumor cells." (PMID 30687086, 2018). "The double-positive feedback loop mediated by the Wnt and AKT/mTOR pathways, two critical signalling pathways in NPC cells, might be used to keep EpCAM at a high level and promote tumour progression, although further experiments are needed to verify this hypothesis." (PMID 29305578, 2018). "As recent studies showed that HDAC inhibitors act in cooperation with PI3K and mTOR inhibitors to inhibit tumor growth in MYC-driven tumors, we tested the HDAC class I inhibitor entinostat (MS-275) at a concentration ineffective for HDAC8 (500 nM) and combined it with the PI3K or mTOR inhibitor." (PMID 29515255, 2018). "According to these foundings, we predicted that CD300A affected the activation of AKT/mTOR signaling pathways by recruiting PTP, thereby regulating the expression of proliferation and apoptosis related genes and affecting the biological behavior of tumor cells." (PMID 29938007, 2018). "In our BRCA2 –mutated xenograft, we did not observe an increased phosphorylation of ERK nor a decreased in BRCA1 gene expression after mTOR inhibition, indicating that this mechanism is not involved in the anti-tumor effect of olaparib and everolimus combination." (PMID 30038706, 2018).
tumor (continued). "We could, then, base our tumor selection for sensitivity on the balance between p-AKT, p-ERK, MYC or mTor, which concomitantly or independently are modulating the sensitivity to rapamycin and irinotecan, and in the absence of an isolated HIF-2α over-expression." (PMID 29069732, 2017). "However, inactivation of PI3K-Akt-mTOR signaling is by far the most reported pathway in several tumor models depending not exclusively on SAHA treatment." (PMID 30563957, 2017). "Therefore, although counterintuitive, emerging evidence supports that PI3K/mTOR inhibition can be optimized to enhance, rather than suppress, the anti-tumor immune response by overcoming immune evasion in a context-dependent fashion." (PMID 28822012, 2017). "Essential signaling pathways involved in tumor cell proliferation and survival, such as epithelial growth factor receptor (EGFR) /Janus kinase 2 (JAK2)/ Signal transducer and activator of transcription 3 (STAT3) and mTOR pathways, have been reported to be propofol’s targets." (PMID 28962554, 2017). "Since ponatinib targets several tyrosine kinases and only FGFR1-activated PI3K/AKT/mTOR and JAK/STAT3 signaling pathways have been investigated in this paper, it is highly likely that the inhibition of other targets also contributed to ponatinib-induced anti-tumor effect in NB." (PMID 27564113, 2017). "Advocating AMPK’s role in tumor suppression is its activation by the well-characterized tumor suppressor LKB1, the clear anti-cancer potential of AMPK activators (e.g., metformin), and the ability of AMPK to inhibit pro-survival downstream targets, namely mTOR." (PMID 29048387, 2017). "In addition to impairing the tumor cell growth of the resistant cells, there is apparent evidence that the combined inhibition of HDAC and mTOR might also have an impact on the metastatic spread." (PMID 29299126, 2017). "In this study, we demonstrated that ectopic expression of miR-99a in HepG2 and Hep3B cell lines and tumor models could suppress cell proliferation, apoptosis, invasive, metastasis and tumor growth by targeting IGF1R and mTOR, which were consistent with the previous observation." (PMID 28624790, 2017). "Additionally, as predicted from in vitro results, SW620 xenografts treated with either euglenophycin or CPT-11 had elevated autophagy demonstrated by increased LC3B and reduced mTOR expression, although euglenophycin alone did not inhibit tumor growth." (PMID 29262645, 2017). "As a tumor suppressor, Merlin has been characterized for its role in mediating contact inhibition of cell growth while eliciting the involvement of receptor tyrosine kinase, PI3K/Akt, small GTPases, cell adhesion, mammalian target of rapamycin (mTOR), and Hippo pathways." (PMID 28112165, 2017). "This tumour is characterised by a combination of increased proliferative tissue and generation of adipose tissue with considerable lipid accumulation that can be suppressed, but not fully blocked, by mTOR inhibitors." (PMID 28302666, 2017). "The expression level of the tumor-suppressor PTEN weakly correlated with the observed changes in mTOR and AKT phosphorylation, and effect that also could not be explained by changes in the phosphorylation of the regulatory site PTEN S380." (PMID 29137331, 2017). "Therefore, mTOR inhibition has both potentially positive and negative effects on tumor immunity, which are worthy of further investigation." (PMID 28337200, 2017). "Besides transcriptional regulation, CMV70-3P might regulate the mTOR pathway, which is critical for CMV infection since that signaling pathway was implemented in cell cycle division, tumor proliferation, invasion and migration." (PMID 27517625, 2017). "Similarly, an inhibitor of phosphatidylinositol-3-kinase (PI3K)/AKT/mammalian target of rapamycin (mTOR) pathway, NVP-BEZ235, inhibited TME-specific signaling pathways such as IL4 and IL6/STAT3, resulting in suppression of angiogenesis, migration, and tumor invasiveness in MCL cells." (PMID 27119356, 2016).
tumor (continued). "However, thus far, parameters reflecting activation of the PI3K/AKT/ mTOR pathway have failed to predict in vivo sensitivity to rapalogs in most tumor types." (PMID 27374081, 2016). "Also, the muscle anabolic response observed upon CDD866 treatment in non-tumor bearing mice was significant and not affected by mTOR inhibition at dose clearly effective on tumor." (PMID 27462398, 2016). "As activation of mTOR has been shown to contribute in tumor progression, it can be speculated that the honokiol-induced inhibition of cell proliferation of HNSCC cells is mediated, at least in part, through the downregulation of EGFR/mTOR signaling pathway." (PMID 27886147, 2016). "LSS exposure was found to induce mechanosensitive Cav-1 activation and PI3K/Akt/mTOR signaling cascade, which increase the MT1-MMP expression and translocation, cytoskeleton reorganization, invadopodia formation and ECM degradation, leading to promotion of tumor cell motility and metastasis." (PMID 26919102, 2016). "A recent critical review indicated that inhibiting a single pathway using mTOR inhibitors may not be sufficient to stop tumor growth; and thus, clinical response may be improved by designing combination therapy protocols." (PMID 26959121, 2016). "To investigate whether the essential role of mTOR in M-MDSC differentiation is limited in allo-graft transplantation settings alone or is a general phenomenon which occurs in other MDSC inducing situations such as tumors, we used tumor-bearing mouse models." (PMID 26833095, 2016). "Interestingly, we found that PD-1/PD-L1 binding could directly activate the intracellular AKT/mTOR signaling, not only in T cells, but also in DLBCL tumor cells." (PMID 27147575, 2016). "In summary, a quick survey of the top 20 results of Xtail provided valuable insights into the molecular responses of PC3 cells to mTOR inhibition, and generated novel but plausible hypotheses about the molecular mechanism of PP242-supressed tumour growth and metastasis." (PMID 27041671, 2016). "Overall, metformin benefits to breast cancer may be due to its role on cellular cycle and PI3K/Akt/mTOR signaling pathway and negative insulin effects on tumour development and growth." (PMID 27725832, 2016). "Therefore, through inactivation of the mTOR pathway, EMC6 reduces the levels of tumor-forming proteins, which subsequently may inhibit GBM formation." (PMID 26775697, 2016). "Although tumor angiogenesis activity is initially decreased with VEGFR inhibition, the development of resistance may be mediated by an upregulation of the phosphoinositide-3 kinase (PI3K)/Akt/mammalian target of rapamycin (mTOR) pathway." (PMID 27295141, 2016). "Therefore, selective AKT inhibition may be superior to mTOR inhibitors in the treatment of CRC, and represents a promising agent to prevent tumor relapse by eliminating the TIC subset." (PMID 27059026, 2016). "These miRNA suppress the expression of mTOR in a post-transcriptional manner and induce apoptosis, thereby decreasing the proliferation of ESCC cell lines, and may play an important role in suppressing the tumor growth." (PMID 27187382, 2016). "LSS exposure was found to induce Cav-1 activation and PI3K/Akt/mTOR signaling cascade and to increase MT1-MMP expression and trafficking, cytoskeleton reorganization, invadopodia formation and ECM degradation, leading to promotion of tumor cell motility and metastasis." (PMID 26919102, 2016). "In this cohort, no adequate p-mTOR expression could be assessed in 290 of the 481 patients (60%) due to absence of tumor cells in the cores and missing cores (clinical characteristics previously published)." (PMID 27096957, 2016). "However, there was no detectable mTOR proteins in the mitochondrial fractions prepared from the tumor cells and tissues." (PMID 25807077, 2015).
tumor (continued). "So far, it is not clear whether mTOR-targeted therapy additionally modulates the microenvironment through inhibiting angiogenesis or modifying polarization of microglial cells towards a tumor-inhibiting M1-phenotype in humans." (PMID 25993328, 2015). "The fact that combined inhibition of PI3K and mTOR signaling did not further improve IL-12p70 secretion by DC-tumor fusions may indicate that inhibition acted on the same signaling pathway, likely to involve p70S6K as has been described previously." (PMID 26605345, 2015). "In tumors where some cells have incurred activating mutations in KRAS, while others have not, miR-100 could accumulate in wild-type KRAS tumor cells through exosomal transfer, inhibiting mTOR and cell growth." (PMID 26132860, 2015). "Our findings demonstrate that activation level of S6 in tumor cells is prognostic of therapeutic response and could be relevant to explore the involvement of PI3K/Akt/mTOR targeting therapy to avoid or delay hormone independence and consequently endocrine resistance." (PMID 26098779, 2015). "Thus, the apoptotic response to GDC-0980 in the tumor fragment spheroid model did not clearly relate to the activity of the PI3K/mTOR pathway." (PMID 26284517, 2015). "In addition to merlin, CRL4 can also upregulate the mTOR pathway through promoting ubiquitination and degradation of tuberous sclerosis 2 (TSC2), a tumor suppressor, that forms a complex with TSC1 which can inhibit the mTOR signaling in a RheB-dependent manner." (PMID 26460955, 2015). "We observed that the expression levels of the phosphorylated active form of MTOR (pMTOR) and YY1 were significantly elevated at as early as one month of age and persistently activated throughout the study period, while MYC and SLC2A1 expression was found upregulated only upon tumor formation." (PMID 25909713, 2015). "In summary, our study suggests that in patients with HCC, miR-216b, which could be transcriptionally reduced by HBx, functions as a tumor suppressor by targeting IGF2BP2 and subsequently suppressing the downstream IGF2, AKT/mTOR and MAPK/ERK signaling pathways." (PMID 25741595, 2015). "Studies show that some MDSC associated miRNAs could interrupt the activity of these signal pathways such as that miR-494 promotes the accumulation and function of tumor-expanded MDSC via targeting PTEN, which results in the subsequent activation of the Akt, NF-κB, and mTOR pathways." (PMID 26285119, 2015). "The reason for this inconsistency is not clear but may be due to mTOR activation independent of AKT by 17β-estradiol that was used for the maintenance of estrogen-dependent MCF7 xenograft tumor growth in vivo." (PMID 25961827, 2015). "This difference between HEK293 cells and our Nf1 mutant tumor cells may reflect the possibility that a Grb10-mediated negative feedback loop acting upon mTOR also requires fully intact Ras regulation, such as neurofibromin." (PMID 26000738, 2015). "Additionally, we examined whether the expression of the invasion proteins MMP-2 and MMP-9 was suppressed by blocking mTOR signaling in secondary NPC tumors and whether tumor sizes and weights were also affected." (PMID 26202311, 2015). "However, all tumor samples were positive for phospho-4E-binding protein 1 (p4E-BP1) and phospho-ribosomal protein S6 (pS6RP), which are targets of the mammalian target of rapamycin (mTOR) pathway." (PMID 25644510, 2015). "Therefore, the mTOR/HDAC inhibitor combination might create a molecular scenario, where particular pro-tumour effects exerted by one drug will be negated by a partner drug." (PMID 24779401, 2014). "p-mTOR expression decreased with increasing stage, and MI tumours were predominantly negative." (PMID 25202348, 2014). "The constitutive activation of the PI3K/Akt/mTOR signaling pathway, which is involved in the regulation of essential cellular functions, is commonly observed in many tumors, including MCL, and is critical for tumor progression and resistance to antineoplastic drugs." (PMID 25216518, 2014).
tumor (continued). "However, it is still possible that a combined inhibition of PI3K and mTOR will produce a much stronger inhibitory effect on tumor growth even in the absence of a specific PI3K inhibitor response." (PMID 24311731, 2014). "The treatment of metastatic RCC (mRCC) has been considerably changed over the last 5 years due to the anti-tumor efficacy of two groups of targeted agents, namely agents that inhibit vascular endothelial growth factor (VEGF) signaling pathways and that inhibit mammalian target of rapamycin (mTOR)." (PMID 24886512, 2014). "Moreover, mTOR, 4E-BP1 and p4E-BP1 were diffusely expressed in the tumor cells." (PMID 24348822, 2014). "Finally, multivariate Cox regression analysis was performed taking into account p-mTOR and p-4E-BP1 expression pre-NAC, p-mTOR expression post-NAC and other clinicopathological features, including tumor grade, receptor status, tumor stage pre-NAC and axillary metastasis." (PMID 25364442, 2014). "However, her tumour had progressed several times before the introduction of the mTOR inhibitor suggesting that this was not the case." (PMID 25104960, 2014). "These therapeutic strategies could be particularly effective when combined with targeted next generation sequencing of tumor samples, since genomic alterations can be detected and help to identify refractory patients with aberrations putatively activating the PI3K/Akt/mTOR pathway." (PMID 25296981, 2014). "Interestingly, the Akt/PI3K/mTOR cascade mediates signalling from leptin and IL-6, which in our have been shown to be significantly elevated in EDBC patients and positively correlated with tumour stage." (PMID 25338520, 2014). "Targeting metabolism using mTOR inhibitors reduced the formation of therapy-resistant polyploidy cells and synergized with BMS-770607, showing that for pancreatic tumor cells targeting tumor metabolism prevents the emergence of therapy-resistant polyploidy tumor cells." (PMID 24904834, 2014). "The apoptosis-inducing mTOR inhibitor Torin-1 hindered growth, motility, invasion, and survival of CD326+/CD24+/CD49f+/CD29+ and CD326+/CD44+/CD166+ CRC subpopulations in vitro, and suppressed tumor growth in vivo with a concomitant reduction in vessel formation." (PMID 24393708, 2014). "Lastly, ablation of Akt2 does not increase mTOR activation as tumor burden increases." (PMID 24722238, 2014). "Additionally, it has been shown that Rap may inhibit angiogenesis, and that the mTOR inhibitors, Rap and RAD001, may significantly enhance the radiosensitivity of the tumor vasculature in vitro and in vivo." (PMID 25009644, 2014). "Angiogenesis occurrence was impaired in pT3/pT4 tumours that did not express p-mTOR." (PMID 25202348, 2014). "In tumor cells, LDH is translationally upregulated by hypoxia inducible factor (HIF) as well as myc and is thus regulated by the phosphatidylinositol 3-kinase (PI3K)/serine/threonine kinases AKT/mammalian target of rapamycin (mTOR)/HIF pathway or myc overexpression." (PMID 25530656, 2014). "Recent data seem to link Akt/mTOR activity directly to GBM motility, which is of particular interest as this would suggest a connection between two almost ubiquitous features of GBM, high activity of the PI3K signaling cascade and tumor dissemination throughout the whole brain." (PMID 26056598, 2014). "Selumetinib was combined with different PI3K/mTOR inhibitors, such as the PI3K inhibitor BEZ235 or the mTOR kinase blocker AZD8055, leading to in vitro synergistic reduction of cell viability, enhanced apoptosis, in vivo tumor regression and extension of median survival." (PMID 24920406, 2014).